HGF (hepatocyte growth factor)
Diseases named in the same sentence as HGF in open-access papers (continued):
Sharing a sentence is not in itself a finding about the gene and the disease.
breast carcinoma (continued). "Previous clinical studies have reported that overexpression of HGF and/or c-Met is associated with the survival rate of patients with malignant tumours, including NSCLCs, breast cancers, and thyroid cancers." (PMID 15083185, 2004). "Furthermore, HGF may also be connected to the biological mechanisms linking a healthy lifestyle and BMI to breast cancer risk." (PMID 40665092, 2025). "Notably, the marginally significant effect of physical activity suggests that regular exercise may further lower breast cancer risk by improving body composition, reducing inflammation, and lowering HGF levels." (PMID 40665092, 2025). "Therefore, promoting a healthy lifestyle that includes physical activity, alongside strategies to control BMI, reduce fat tissue inflammation, and regulate HGF signaling, may effectively lower breast cancer risk in the population." (PMID 40665092, 2025). "HGF expression is a defining feature of basal-like tumors, and its association with black race and young women suggests it may be a candidate pathway for understanding breast cancer disparities." (PMID 34344422, 2021). "Regional Manhattan plots examining the association of all SNPs ±100 kb from the SNP used to instrument HGF for their association with this adipokine and with ER− breast cancer did not appear to support the presence of one or more independent causal variants for SNP‐ER− breast cancer analyses." (PMID 32134113, 2020). "To address this hypothesis, we genotyped tagging SNPs (tagSNPs) of five TTSP genes, TMPRSS1, TMPRSS2, TMPRSS3, TMPRSS7, and TMPRSS11E, two other serine proteases uPA and PRSS8, and HGF, and investigated their association with breast cancer risk and patient survival." (PMID 25029565, 2014). "Observation that HGF production increased in co-cultured ASCs is parallel with the previous observation that breast cancer cells susceptible to ASCs expressed higher levels of c-Met, suggesting a master role for HGF/c-Met pathway in crosstalk between ASCs and breast cancer cells." (PMID 24327602, 2014). "Crosstalk between adipose-derived stem cells (ASCs) and breast cancer cells, mediated via HGF/c-Met signaling, further regulates tumor self-renewal potential." (PMID 41373619, 2025). "This selectivity increased at 48 h, reaching an SI of 20.0 for ARPE-19 and 8.0 for hGF, highlighting a time-dependent enhancement in cytotoxic selectivity toward breast cancer cells." (PMID 40005959, 2025). "In preclinical and clinical studies, the HGF/c-MET signaling pathway has been found to play a significant role in breast cancer tumorigenesis and disease progression, contributing to the invasive phenotype seen in many tumors." (PMID 40361420, 2025). "There are significant differences in serum HGF levels between breast cancer patients and healthy people, especially in postmenopausal women, poorly differentiated tumors, and distant metastatic breast cancer patients." (PMID 40860340, 2025). "Given the associations between CCL2 and HGF expression in breast tissues, we compared the effects of CCL2 and HGF co-treatment with a single treatment on breast cancer cell lines." (PMID 40736024, 2025). "In mammary carcinoma-associated fibroblasts, TGF-β negatively regulates CXCL1 expression through Smad2/3 and HGF/c-Met signaling mechanisms." (PMID 40490643, 2025). "Despite the limited number of studies evaluating the efficacy of TAS-115 on various cancer types, no research has specifically investigated its effects on c-MET/HGF-mediated breast cancer progression and metastasis, either alone or in combination with DOXO." (PMID 41289612, 2025). "The hepatocyte growth factor (HGF)/MET signaling pathway is also involved in the regulation of breast cancer by CAFs." (PMID 40890855, 2025). "In summary, our research highlights the essential role of HGF as a biomarker for the early detection of breast cancer, particularly in postmenopausal women." (PMID 40665092, 2025).
breast carcinoma (continued). "Given the alterations in AKT, AMPK, p42/44MAPK and PKC signaling with CCL2 and HGF treatment, we determined the contributions of these pathways to CCL2 and HGF-mediated metabolism in breast cancer cells." (PMID 40736024, 2025). "The role of HGF/c-Met crosstalk with ASCs is intriguing for its potential link to recurrence as confirmed from immunostaining in primary breast cancer tissues." (PMID 41373619, 2025). "Overall, these data indicate that CCR2 overexpression increases responsiveness to CCL2 and HGF in SUM225 breast cancer cells." (PMID 40736024, 2025). "The results provide valuable insights into the molecular mechanisms underlying the effects of TAS-115 on breast cancer progression, particularly in terms of apoptosis, cell survival, and the c-MET/HGF signaling axis." (PMID 41289612, 2025). "Taken together, AKT, p42/44MAPK and AMPK signaling are important for CCL2/HGF-mediated glycolysis in breast cancer cells." (PMID 40736024, 2025). "In MDA-MB-231 human breast cancer cells, HGF stimulated the transportation of the PAK1/WAVE2 complex to the leading edge of lamellipodia through phosphorylation of STMN1S38." (PMID 40723207, 2025). "CAFs secrete HGF, enhancing breast tumorigenesis and colony formation, suppressing the luminal phenotype and sustaining the triple-negative status of breast cancer cells." (PMID 40230452, 2025). "For instance, CAFs can secrete factors such as hepatocyte growth factor (HGF), activating signaling pathways like c-Met, which is associated with increased radioresistance in breast cancer." (PMID 40788933, 2025). "It would be of interest to conduct further studies on how CCL2 and HGF regulate breast cancer cell activity through genetic and epigenetic mechanisms." (PMID 40736024, 2025). "Both paracrine and autocrine HGF-dependent MET signaling play significant roles in breast cancer progression." (PMID 40560045, 2025). "Overall, these studies provide insight into how CCL2 and HGF function to coordinate breast cancer growth, survival, invasion, and metabolism, and demonstrate that targeting CCR2 and MET inhibit DCIS progression." (PMID 40736024, 2025). "Recent targeting of HGF/c-Met interaction has emerged as a significant breakthrough in breast cancer therapy." (PMID 38533507, 2024). "The HGF-Met pathway significantly affects glucose and lipid metabolism, with HGF enhancing glucose consumption and lactate production in breast cancer cells (“Warburg effect”)." (PMID 38654922, 2024). "Apigenin has been shown to inhibit hepatocyte growth factor (HGF)-induced invasive growth of human breast cancer cells, including motility, spreading, migration, and invasion." (PMID 38791608, 2024). "Targeting the HGF/c-Met signaling pathway emerges as a promising strategy for enhancing the radiosensitivity of breast cancer cells." (PMID 39408826, 2024). "These inhibitory effects have contributed significantly to the suppression of migration and invasion abilities in HGF-induced breast cancer cells." (PMID 39203892, 2024). "HGF stimulates cell migration in breast cancer cells and oleocanthal attenuates this effect by suppressing the phosphorylation of Brk, paxillin, Rac1, and c-Met." (PMID 39203892, 2024). "Extracellular superoxide dismutase inhibits hepatocyte growth factor-mediated breast cancer-fibroblast interactions." (PMID 37469162, 2024). "Data from The Cancer Genome Atlas (TCGA) database demonstrated upregulation of CCL8 and TGFBI and downregulation of HGF in breast cancer." (PMID 37884960, 2023). "To accomplish this, we examined the antitumor effects of foretinib in MDA-MB-231 xenograft tumors in vivo and then investigated the effects of foretinib on p-MET/HGF signaling in both breast cancer cells and xenograft tumors." (PMID 36614199, 2023). "In fact, a study in African American women with obesity showed that adipose tissue secretes hepatocyte growth factor (HGF) with an endocrine effect on breast cancer cells." (PMID 36670988, 2023).
breast carcinoma (continued). "Disruption of an HGF gene promoter region termed DATE (for deoxyadenosine tract element) that acts as a transcriptional repressor and consists of 30 tandem deoxyadenosines has been reported to increase HGF expression in breast cancer." (PMID 36672409, 2023). "Breast cancer cells secrete IL-1β, in response to which astrocytes secrete HGF, which in turn increases IL-1β expression in breast cancer cells." (PMID 37108425, 2023). "The involvement of MACC1 in regulating the HGF/c-Met signaling pathway has been confirmed in cancers such as colon cancer, breast cancer, ovarian cancer, lung cancer, liver cancer, gastric cancer, mesocortical tumor, malignant brain tumor, and kidney cancer." (PMID 36979146, 2023). "Circulating VEGF, HGF, and Ang-2 levels have been described in breast cancer, hepatocarcinoma, and melanoma." (PMID 35372407, 2022). "This work unveils a new link between MET and NMDAR in breast cancers and highlights a new role of glutamate receptor in the proinvasive response to HGF." (PMID 36139568, 2022). "In breast cancer cell lines, for example, HGF/c-MET interaction has been demonstrated to preferentially increase adhesion to laminins, fibronectin, and vitronectin via a PI3K pathway." (PMID 35630066, 2022). "Hepatocyte growth factor (HGF) and Met are potential candidate targets for therapeutic and pharmacological intervention in breast cancer therapy." (PMID 35369062, 2022). "In conclusion, our studies in breast cancer cell lines identified the CDCP1-SRC-ARHGEF7-RAC1 axis as a crucial mediator of HGF-induced cancer cell migration and invasion." (PMID 35085554, 2022). "Recent studies have concluded that ASCs assist breast cancer recurrence and progression via the HGF/c-MET pathway." (PMID 36077676, 2022). "The MET oncogene, encoding the tyrosine kinase receptor for a hepatocyte growth factor (HGF), plays a key role in the onset and progression of aggressive forms of breast cancer." (PMID 36139568, 2022). "Altogether, these results demonstrate that the CDCP1-SRC-ARHGEF7-RAC1 pathway plays an important role in the HGF-induced invasion of a subset of breast cancer cells." (PMID 35085554, 2022). "High levels correlated with the appearance of metastases, and 29 of 35 patients with recurrent breast cancer had an increase in serum HGF level." (PMID 35818030, 2022). "In a study of 130 patients with HER-2-positive breast cancer, both MET and HGF amplification were associated with trastuzumab failure and patients with MET amplified tumors had a shorter time to progression." (PMID 35069735, 2022). "In contrast, HGF-fibronectin cooperativity is also exhibited by cells in anchorage-independent conditions, resulting in increased mammary carcinoma cell survival." (PMID 36330337, 2022). "Here, we show that HGF-promoted migration and invasion of breast cancer cells are regulated by CUB domain–containing protein 1 (CDCP1), a transmembrane activator of SRC kinase." (PMID 35085554, 2022). "As demonstrated in several studies, higher HGF levels in serum of patients suffering from mammary cancer are correlated with worse survival and distant metastasis." (PMID 35568918, 2022). "This study observed that the novel HGF gene expression signature was a defining feature in basal-like breast cancer tumors." (PMID 34344422, 2021). "In breast cancer cell lines, activation of the HGF pathway via binding of HGF to its receptor c-MET can lead to increased cell survival, proliferation, and resistance to cancer inhibitors." (PMID 34344422, 2021). "In the xenograft model of bone metastasis from breast cancer, the blockade of the HGF/Met axis or TGF-β prolongs the survival of animals." (PMID 34572548, 2021). "The distribution of HGF also highlights some long-standing breast cancer outcome disparities; HGF positivity is more prevalent among black participants and among women under the age of 50 (and especially those under 40)." (PMID 34344422, 2021).
breast carcinoma (continued). "The addition of HGF in the culture medium increased the number of tumorspheres formed by breast cancer PDX cells cocultured with Cfd-KO mADSCs." (PMID 34439392, 2021). "To evaluate the role of HGF pathway activation in breast cancer disparities, we assessed a 38-gene HGF gene expression signature in invasive breast cancer cases in a population-based resource, the Carolina Breast Cancer Study." (PMID 34344422, 2021). "HGF/MET signaling disrupted TJs in the breast cancer cell lines MDA-MB-231 and MCF-7 by downregulating the expression of several important TJ molecules, such as occludin, at both transcript and protein levels." (PMID 33917539, 2021). "There is a need for biomarkers to improve efficacy to target the c-MET/HGF signaling pathway, especially within breast cancer." (PMID 34344422, 2021). "The HGF/c-MET axis is an attractive pathway in breast cancer research because it is targetable with existing therapeutics." (PMID 34344422, 2021). "HGF rescued the reduced ability of Cfd-KO mADSCs to promote tumorsphere formation in vitro and tumor formation in vivo by breast cancer PDX cells." (PMID 34439392, 2021). "For example, overexpression of growth factor TGFβ and hepatocyte growth factor (HGF) in mouse fibroblasts was shown to induce breast cancer when co-injected with normal epithelium." (PMID 33806468, 2021). "The hepatocyte growth factor (HGF) has also been found to regulate the CXCR-4 expression by activating PKC-ζ in breast cancer cells." (PMID 34885003, 2021). "In a xenograft model of bone metastasis from breast cancer, HGF, more available in the bone microenvironment with respect to control bone, activates β-catenin signaling in cancer cells." (PMID 34572548, 2021). "Analysis of publicly available breast cancer expression profiles revealed that high expression of both FGFR1 and HGF were associated with poor relapse-free survival (RFS) specifically in basal tumours." (PMID 33772015, 2021). "Taken together, this population-based study contributes important information on the distribution of HGF-positive tumors in breast cancer." (PMID 34344422, 2021). "In the Carolina Breast Cancer Study, 32% of participants were classified as HGF-positive by our 38-gene assay." (PMID 34344422, 2021). "In female breast cancer, HGF and c-MET have been identified as a predictor for worse outcomes and are associated with a high Ki-67 labeling index." (PMID 32188473, 2020). "The MET ligand hepatocyte growth factor (HGF) plays a vital role in promoting breast cancer progression and metastasis." (PMID 32655941, 2020). "Pai in his study in 2020 also showed that preoperative HGF levels are higher in patients with more advanced breast cancer with metastases compared to patients with less advanced cancer." (PMID 32607415, 2020). "For example, in MCF-7 breast cancer cells and other cell types, E-cadherin associates with MET and this interaction increased after HGF treatment leading to HGF-MET signaling amplification." (PMID 32823931, 2020). "Experimental studies have indicated that radiation can induce overexpression of Met in tumour cells from several cancer forms, including breast cancer, pancreas cancer and nasopharyngeal cancer, leading to increased sensitivity to HGF and higher invasiveness." (PMID 32946618, 2020). "In our cohort in male breast cancer, we identified HGF to be an independent prognostic factor for better OS." (PMID 32188473, 2020). "In this unique cohort of male breast cancer patients, we identified HGF expression in the primary tumor to be an independent predictor for better OS in the non-metastatic setting." (PMID 32188473, 2020). "Many studies have shown that the interaction between ncRNAs and HGF/c-Met axis exerts regulatory effects on breast cancer progression and clinical therapy." (PMID 32083078, 2020).
breast carcinoma (continued). "HGF promotes the tumor growth by stimulating neovascularization and it was found that the levels of HGF expression in breast cancer patients were elevated as compared to the normal people." (PMID 31372176, 2019). "The HGF/Met signaling pathway in CAFs is involved in GFT resistance in triple-negative breast cancer, and secreted HGF confers resistance by increasing Met phosphorylation in breast cancer cells." (PMID 30927928, 2019). "We give insights into the roles of HGF and TGFβ1 in determining Twist and Snail profile at the center and invasive front of bone metastasis from breast carcinoma." (PMID 31121879, 2019). "Here, we report that BFE suppresses HGF-enhanced cell migration, adhesion, vessel formation and invasion of breast cancer cells in vitro through inhibition of HGF/c-Met signalling and reduction of c-Met receptor phosphorylation." (PMID 30314527, 2018). "It was proposed that the elevation in WWOX expression is responsible for altering the HGF/Met/E.cadherin signaling axis and thus reducing breast cancer metastasis to the bone." (PMID 30619734, 2018). "Hepatocyte growth factor (HGF) plays a pivotal role in breast cancer cell motility, invasion and angiogenesis." (PMID 30314527, 2018). "Following HGF treatment, the breast cancer cells displayed a significant increase in migration, matrix adhesion, vessel/tubule formation, invasion and c-Met activation." (PMID 30314527, 2018). "Our findings reveal that BFE was able to significantly suppress the influence of HGF in breast cancer cell motility and invasion in vitro, through the ability of BFE to reduce HGF/c-Met signalling events." (PMID 30314527, 2018). "Upon HGF stimulation, these breast cancer cells revealed a dramatic and significant increase in motility, cell–matrix adhesion and invasiveness; this increase was governed through HGF-Met coupling and subsequent activation of the c-Met receptor." (PMID 30314527, 2018). "Using the hanging drop 3D culture system we investigated the potential of the breast cancer cells to grow and form spheroid structures when cultured under the influence of HGF." (PMID 30314527, 2018). "Further study revealed that the BFE inhibited these HGF-enhanced effects through suppression of c-Met receptor tyrosine kinase phosphorylation (pY1234/5) within these breast cancer cells." (PMID 30314527, 2018). "Once again, these results suggest that the presence of BFE was able to limit the pro-metastatic influence of HGF on breast cancer cells." (PMID 30314527, 2018). "Matriptase was highly expressed in breast cancer cell lines and involved in cancer progression through activation of the HGF/MET signaling axis." (PMID 30469509, 2018). "In breast cancer, the HGF/MET pathway activates the bone microenvironment through the Wnt-β-catenin pathway, and has an important role in the plasticity of bone metastasis." (PMID 29890660, 2018). "For example, the expression of HGF reduced sensitivity of several HER2-dependent breast cancer cell lines to lapatinib." (PMID 30227653, 2018). "Overexpression of miR‐128‐3p reduced MET expression and abrogated HGF‐induced cell migration of invasive breast cancer cells." (PMID 30004628, 2018). "The mean migration rate per hour was determined for each treatment group and we report that the presence of HGF significantly (p = 0.0035) enhanced the migration rate (49.31 μM/h) of these breast cancer cells compared to the control group (27.01 μM/h)." (PMID 30314527, 2018). "The stromal cells of mammary tumours produce a rich array of cytokines; one of the best documented is a cytokine known as hepatocyte growth factor (HGF)." (PMID 30314527, 2018). "The objective of this study is to determine the effect of EcSOD and oxidative stress on HGF/c-Met-signaling in breast cancer." (PMID 29296173, 2017).